KRAS (KRas proto-oncogene, GTPase)
Diseases named in the same sentence as KRAS in open-access papers (continued):
Sharing a sentence is not in itself a finding about the gene and the disease.
cancer (continued). "Our data suggest that unlike for KRAS-mutated cancer cells, where FMD reverts the vitamin C-mediated HO-1 upregulation, KRAS-wild-type tumors are more resistant to oxidative insults, possibly because of their ability to rapidly neutralise radical species." (PMID 32393788, 2020). "Targeting KRAS directly is thus a great challenge and after more than three decades of research, KRAS-inhibitors have still not been implemented in cancer treatment." (PMID 32079091, 2020). "Three amplicons (KRAS, MAPK1, and CCND1) have been observed in cancer of oral cavity from Taiwanese patients, and therefore, all could possibly contribute to activation of EGFR signaling." (PMID 32974098, 2020). "Endogenous TRAIL-R2 was shown to promote KRAS-driven cancer through cancer cell-autonomous Rac1 activation and non-cancer-cell-autonomous reprogramming of the TIME into one conducive of type 2 macrophage accumulation." (PMID 32194994, 2020). "This work suggests that NF1 activity on KRAS G13D does not occur to a large extent, and that it is not occurring within cancer cells as no changes in KRAS-GTP were detected even at high levels of NF1 expression." (PMID 33153459, 2020). "Unfortunately, FTIs failed in clinical trials showing no efficacy against NRAS and KRAS-driven cancers." (PMID 32850962, 2020). "Although it was identified in several sequencing studies of cancer patients, it does not lie within any known functional domains of KRAS and has not been biochemically characterized." (PMID 32144301, 2020). "Accounting for context highlights a DNA repair pathway as a dependency in KRAS mutant cancers, which is reproducibly observed in multiple studies but not always the top hit and therefore not immediately apparent." (PMID 32398776, 2020). "Here, we for the first time demonstrated combinative treatment of β-elemene and cetuximab induced ferroptotic cell death in KRAS mutant CRC cell HCT116, accompanied with decreased cell viability and increased iron-dependent accumulation of lipid peroxidation in these cancer cells." (PMID 32308771, 2020). "Combining KRAS with PTEN further enhanced the percentage of malignant tumors but not the percentage of non-neoplastic lesions." (PMID 32823526, 2020). "We find that common cancer mutations including BRAF-V600E and KRAS-G12D are predicted to bind none of the common HLA alleles, and are thus “immunogenically silent” in the human population." (PMID 32256484, 2020). "The prevalence of mutant KRAS in normal individuals suggests that mutant KRAS per se is not sufficient for full-blown cancer development." (PMID 32764295, 2020). "For example, in MTP19, KRAS p.G12V was present in the majority of IPMN samples, as well as all the invasive cancer samples, but there were an additional four other KRAS mutations (all occurring in hotspot positions) that were present in a small number of sections in low-grade IPMN samples." (PMID 32796935, 2020). "In our study, we did not observe that KRAS mutation increased PD-L1 expression, nor a solid correlation of ACAA1 with PD-L1 expression in cancer cells using GEPIA (TCGA datasets)." (PMID 33194642, 2020). "The lack of KRAS antibodies working in a large panel of applications is surprising because of its importance in the carcinogenesis process of many cancers; the reasons behind this lack are multiple." (PMID 32887255, 2020). "In KRAS-wild-type cancer cells HO-1 levels were not altered upon vitamin C administration under CTR condition, and the combination of vitamin C and STS did not downregulate but instead induced HO-1 protein expression level." (PMID 32393788, 2020).
cancer (continued). "In addition to hTERT, some G4 ligands that more selectivity target to particular G4s at the promoter of specific cancer-related genes (e.g. C-MYC, BLC2, KRAS, and VEGF) have been reported." (PMID 32257105, 2020). "The KRAS degrader specifically reduced proliferation of cells with mutant KRAS expression in 2D-adherent and 3D spheroid assays but did not modify the proliferation of cancer cell lines with mutant NRAS or HRAS nor of the RASWT cells HCC827 and MRC5." (PMID 32591521, 2020). "Importantly, the expression of GS in cancer seems to be regulated by oncogenic players such as Myc, KRAS, and PI3K, indicating that the cancer cells’ genetic profile can limit the expression of GS and consequently their capacity of de novo producing glutamine." (PMID 32993063, 2020). "Although targeting IL-8 has not been investigated specifically in KRAS-mutant cancers yet, one study utilised the IL-8 inhibitor BMS-986253 as a single agent in advanced malignant solid tumours." (PMID 33116132, 2020). "Thus, our studies suggest that in addition to directly targeting oncogenic KRAS and its downstream effectors and glycolytic pathways, targeting the upstream inducers of KRAS hyperactivation may constrain the heightened aerobic glycolysis for cancer prevention and therapy." (PMID 30819189, 2019). "Nevertheless, the challenge of clinical treatment of KRAS-mutant cancers seems not to be insurmountable." (PMID 31612108, 2019). "Moreover, PDE6D expression correlated significantly with KRAS expression levels in HCC tissues, which is in accordance with the finding that PDE6D serves as a novel targetable KRAS transport chaperon in cancer cells." (PMID 30901922, 2019). "In fact, parental SW48 and LIM1215 cancer cells were significantly sensitive to cetuximab, panitumumab, SYM004 and MM-151 antibodies inducing growth inhibition, as expected being “quadruple wild type” for KRAS, BRAF, NRAS and PIK3CA genes." (PMID 31164152, 2019). "Overall, these ratios calculated for the whole group of 19 NSCLC patients (7 KRAS-mutation negative and 12 KRAS-mutation positive) were 18/19 (EBC versus cancer), 10/19 (blood versus cancer) and 9/19 (EBC versus blood), respectively (p = 0.001)." (PMID 30368666, 2019). "They do not recognize a cancer cell line expressing the wild type KRAS G12 protein and the HLA-A*02:01 complex." (PMID 31803176, 2019). "According to previous study, a key point for targeting cells stuck in the S-phase is the specificity for KRas-driven cancer cells, in that these cancer cells do not arrest in the G1 phase." (PMID 31489935, 2019). "Moreover, among the down-regulated genes in the KRAS G13D-expressing HKe3 cells, the most enriched pathways were the type I interferon signaling pathway and the antigen processing and presentation pathway, which may help cancer cells to evade the host immune response." (PMID 31681616, 2019).
cancer (continued). "An increase in KRAS expression and production of the related protein may lead to increasing CIN in cancer cells, which may destroy the DNA at the chromosome surface, or part of it, leading to cell apoptosis and inhibition." (PMID 31330954, 2019). "KRAS, as a typical oncogene to initiate cancer development, has been proven in many cancer types, especially in CRC, with strong early diagnosis impact, even in the cancer progression and prognosis." (PMID 31207989, 2019). "Constitutively active MAPK signaling in KRAS-mutated CRC promotes epithelial–mesenchymal transition and cancer stemness, independent of external EGFR stimulation." (PMID 31771279, 2019). "Some of these targets are oncogenes, for example, CCND1 and KRAS, or tumour suppressors such as PTEN and HSP90AA1, and the deregulation of these genes may contribute to cancer pathogenesis." (PMID 30845775, 2019). "MiR-425-5p-based treatments might have a strong potential in targeting KRAS-driven CRC to overcome the drug resistance and to dissect and control the molecular network related to cancer progression." (PMID 31673240, 2019). "Although KRAS is an excellent drug discovery target for many cancers, and despite decades of research, no therapeutic agent directly targeting RAS has been clinically approved." (PMID 31332011, 2019). "Despite decades of endeavors to target KRAS for cancer therapy, the efforts have not been very successful, partly due to the challenges to locate pharmacologically suitable docking site for small molecular drugs." (PMID 30674639, 2019). "There are no reports of a relationship between KRAS DNA copy number and histological phenotype in other cancer types and in GC it has not been investigated in a large study." (PMID 31111275, 2019). "Additionally, these results demonstrate that in vivo therapeutic benefit for the combination of MEK and TNKS inhibition in KRAS and PIK3CA mt cancers." (PMID 30944457, 2019). "That's might be the reason why knockdown of NEAT1 or increase of miR‐193a‐3p could impede cancer progression in colorectal carcinogenesis and offer genetic evidence that NEAT1 is one of the critical regulators to control oncogene KRAS." (PMID 30575330, 2019). "Nevertheless, in this study expanding the molecular analysis with genes from the Ampliseq cancer hotspot panel v2 beyond KRAS and GNAS did not significantly improve the detection of mucinous PCN (data not shown)." (PMID 31258847, 2019). "Therefore, RAS testing including KRAS exons 2, 3 and 4 (codons 12, 13, 59, 61, 117 and 146) is mandatory before treatment with anti-EGFR therapy in cancer patients." (PMID 31673240, 2019). "Despite these potentially effective options to target KRAS mutant cancer cells, none of them have yet been translated into clinical practice." (PMID 31847096, 2019). "Even though K13/K19 bind to both mutant and WT KRAS, they only prevent RAS-dependent signalling in KRAS mutant cancer cells (HCT116) and do not affect RAS signalling in RASWT cancer cells (MCF-7)." (PMID 31197133, 2019). "However, multiple published studies have used different genes (e.g., KRAS, BRAF, APP, ACTB, GAPDH, 16s rRNA, ALU, LINE 1) as biomarkers to determine cfDI in various cancers." (PMID 31620364, 2019). "We were able to extract DNA and perform an exploratory analysis of the cancer gene mutational status on archival biopsy samples from 11 of 16 patients and did not detect EGFR, KRAS or ALK gene alterations in any cases." (PMID 30647837, 2018). "Surprisingly, many well-known cancer proteins such as KRAS, KLK3 (prostate-specific antigen, PSA), and HSP90 did not exhibit significant changes in the immediate response after 24 h post pharmacological treatment." (PMID 29977602, 2018).
cancer (continued). "The identification of molecular targets in the ErbB and MAPK cascade is not surprising in a KRAS mutant cancer cell." (PMID 29599906, 2018). "Taken together, these data suggest that KRAS-mutant cancer cells respond to pleural IL-1β via IKKα-mediated non-canonical NF-κB activation." (PMID 29445180, 2018). "Unbiased analyses identified cancer-elaborated CXCL1/PPBP, potent myeloid cell chemoattractants that drive inflammation and metastasis via CXCR1/CXCR2 on host cells, as the transcriptional targets of IL-1β-fostered KRAS-IKKα addiction." (PMID 29445180, 2018). "This is in line with a recent publication which concluded that BMS-906024 not only sensitizes NSCLC to paclitaxel, but that this occurs more potently in KRAS and BRAF wildtype cancers therefore, possibly being able to predict better patient outcomes to dual combination therapy." (PMID 30464927, 2018). "Although cilia house a number of oncogenic molecules (including Smoothened, KRAS, EGFR, and PDGFR), their precise role in cancer remains unclear." (PMID 29874589, 2018). "A higher rate of KRAS mutation was found in stage II (48.49%) compared with that in stage I, stage III and stage IV (36.84%, 40.45%, 34.52%, respectively) cancers (p = 0.023) and in non-smokers compared with smokers (46.6% vs34.98%, p = 0.001)." (PMID 29423347, 2018). "It is clear that the ratio of both isoforms is altered in cancer and, while the focus-inducing potential of KRAS-4B is lower than that of KRAS-4A, the latter isoform do not induce cell migration and KRAS-4B does." (PMID 29755673, 2018). "Among the 17 pretreatment plasma samples, we detected ctDNA in ten, twelve, and fifteen samples when profiling MP/KRAS, MP/FNA, and MP/TR, respectively, indicating an increased sensitivity of cancer detection by analyzing cfDNA across broad genomic target regions." (PMID 30072705, 2018). "Finally, KRAS mutations were significantly depleted (p = 0.003; Fisher’s exact test) among the cell lines exhibiting net cell death in response to GSK525762, suggesting that activated RAS signaling may be a mechanism by which cancer cells are able to survive BET inhibition." (PMID 29674704, 2018). "In conclusion, we show that KRAS-mutant cancer cells use host IL-1β to sustain IKKα-mediated non-canonical NF-κB activity responsible for MPE development and primary drug resistance." (PMID 29445180, 2018). "In human cancers, oncogenic mutations commonly occur in the RAS genes KRAS, NRAS, or HRAS, but there are no clinical RAS inhibitors." (PMID 30194290, 2018). "For K-Ras4A expression, LUAD showed strong association with KRAS amplification (S = 0.781, r2 = 0.945), but no or weak correlation was observed in other cancer types." (PMID 29504894, 2018). "In a separate study, uterine lavage fluid, which contains mostly endometrial cells, showed abundant cancer driver mutations mostly in PIK3CA, KRAS, and PTEN both in women with and without endometrial cancer." (PMID 29300727, 2018). "To understand if NF1 shallow deletions correlate with deregulated RAS signaling, we employed expression signatures developed from KRAS-mutant cancers and performed a secondary WGCNA analysis and unsupervised clustering with 788 genes related to ER, RAS and KRAS signaling pathways." (PMID 30182054, 2018). "No cancer-associated EGFR gene mutation or copy-number variation, nor any KRAS, BRAF, NRAS hotspot mutations were found in any microdissected area." (PMID 29492209, 2018). "A research in 2011 indicate that oncogenes like KRAS, MYC and BRAF can promote the expression of NRF2 to degrade ROS to make a more reduced intercellular environment, therefore, protects cancer cell from oxidative stress and promote cell proliferation and tumorigenecity." (PMID 29416692, 2018). "However, we demonstrate an isolated requirement for IKKα in KRAS-driven MPE, an important cancer phenotype." (PMID 29445180, 2018).
cancer (continued). "The co-existence of mutant KRAS and elevated IKKα-mediated non-canonical NF-κB signaling in the cancer cell, relentlessly driven by host IL-1β, leads to two important consequences." (PMID 29445180, 2018). "It has been shown that both YAP1 and KRAS have a common biding site which is the E2F transcription factor and that in the absence of KRAS signaling YAP1 functionally replaces KRAS in KRAS-dependent cancer cells." (PMID 29850494, 2018). "In contrast, the altered extent to KRas activation in wild-type KRas BxPC-3 cell line was not as strong as in mutant KRas cancer cell lines at the low concentrations." (PMID 29467941, 2018). "Collectively, these data indicate that mutant KRAS induces non-canonical NF-κΒ signaling of cancer cells in unstimulated and IL-1β-stimulated conditions." (PMID 29445180, 2018). "In our study, KRAS did not change cancer cell characteristics in 2D culture; however, it dramatically altered characteristics in 3D culture, consistent with the results of previous studies." (PMID 30509235, 2018). "KRAS and MYC have been extensively studied with regard to cancer." (PMID 30788462, 2018). "Both of these effects were phenocopied in NRAS‐ and KRAS‐mutant cancer cells by dabrafenib, but not vemurafenib." (PMID 29112787, 2018). "Here the mechanism of pleural IL-1β function in MPE promotion is elucidated: CCL2-attracted monocyte-released IL-1β fosters NF-κΒ activation of MPE-prone KRAS-mutant carcinomas by potentiating non-canonical NF-κB signaling via IKKα." (PMID 29445180, 2018). "While additional work is needed to assess the functional relevance of both PEAK1 and MST1R in the context of KRas wild type cancers, these data predict that PEAK1 may be a more potent driver of initiation and progression under these wild type KRas conditions." (PMID 27602776, 2017). "A missense variant in Epidermal Growth Factor EGF (p.Pro1096Thr), the upstream regulator of the NRAS/KRAS pathway, is predicted pathogenic by SIFT/PolyPhen-2 but has not been reported in association with cancer by the COSMIC or TCGA datasets." (PMID 29254223, 2017). "Given the challenge of inhibiting KRAS directly and the role of MYC in various aspects of cancer progression, therapy for treating KRAS-driven cancers may also be expected to depend on MYC." (PMID 28152508, 2017). "Asn was shown to be up-regulated in KRAS-mutant CRC via the overexpression of asparagine synthetase (ANSN) and it promotes protein biosynthesis in cancer cells by serving as an amino acid exchange factor regulates the uptake of amino acid and cell proliferation." (PMID 29254168, 2017).